TP53TG3B (TP53 target 3B)
Gene: Protein-coding gene on chromosome 16 (33,360,841 to 33,363,478, forward strand). Ensembl gene ENSG00000261509.
Subcellular location: Cytoplasm; Nucleus
Subcellular location (Human Protein Atlas): Centriolar satellite
Gene Ontology:
Cellular component: cytoplasm; nucleus
Homologues: Paralogues in human: TP53TG3 (100% identical), TP53TG3C (100% identical), TP53TG3D (100% identical), TP53TG3E (100% identical), TP53TG3F (100% identical).